SPINK1 (serine peptidase inhibitor Kazal type 1)
Diseases named in the same sentence as SPINK1 in open-access papers (continued):
Sharing a sentence is not in itself a finding about the gene and the disease.
prostate tumor (3 papers, 2013 to 2018). "The expression of Spink1 in prostate tumors has shown promise as an independent predictor of biochemical recurrence after resection; most excitingly, is able to be detected in the urine—making it a less-invasive alternative to sampling previous biomarkers." (PMID 24018887, 2013). "Serine protease inhibitor Kazal type 1 (Spink 1), has been shown to be present in a subtype of prostatic tumors not containing a TMPRSS2:ETS fusion." (PMID 24018887, 2013). "Hence, our results evidently suggest that specific elimination of SPINK1 from the whole spectrum of SASP in the treatment-damaged TME increases tumour response to chemotherapy, a result independent of androgen response or AR signaling of prostate tumours per se." (PMID 30333494, 2018).
acute lymphoblastic leukemia (2 papers, 2022 to 2024). Leukemia with an acute onset, characterized by the presence of lymphoblasts in the bone marrow and the peripheral blood. "In co-culture system of HUVECs and Acute lymphoblastic leukemia (ALL) cells, SPINK1 exposure also resulted in enhanced endothelial cell motility and ALL cells trans-endothelial migration." (PMID 35194087, 2022).
adenoma (2 papers, 2022 to 2023). A neoplasm arising from the epithelium. "It mediated autocrine invasion and metastasis and was negatively regulated by anti-SPINK1 antibody and function-blocking mutant KY-SPINK1 at the serine -protease interaction site involving adenoma-carcinoma transition." (PMID 36053457, 2022). "And finally, SNORD123, CEACAM6, SNORD78, ANXA10, SPINK1, and CPS1 genes can be used as biomarkers for normal-adenoma comparison." (PMID 37565794, 2023).
colon adenocarcinoma (2 papers, 2015 to 2021). "The knockdown of SPINK1 expression by another study showed a significant decrease in the proliferation of colon adenocarcinoma WiDr cells, whereas the SPINK1-enriched conditioned medium increased the oncogenic phenotype." (PMID 33916984, 2021). "Taken together, these findings demonstrate that endogenous or exogenous presence of SPINK1 has an important role in cell proliferation and invasion during colon adenocarcinoma progression." (PMID 26258891, 2015). "We next assessed SPINK1 expression across various colon adenocarcinoma cell line models (n=20) available at Oncomine." (PMID 26258891, 2015). "Stable knockdown of SPINK1 significantly decreases cell proliferation, invasion and soft agar colony formation in the colon adenocarcinoma WiDr cells." (PMID 26258891, 2015). "Next, to investigate the SPINK1-mediated global gene-expression profiles in colon adenocarcinoma, microarray analysis was performed using shSPINK1-1, shSPINK1-3, shSPINK1-6 and shSCRM cells on Agilent Human Whole Genome Oligo Expression Arrays (Agilent Technologies, Santa Clara, CA, USA)." (PMID 26258891, 2015).
colorectal adenocarcinoma (2 papers, 2015 to 2018). The most common type of colorectal carcinoma. "Thus, finding an effective way to inhibit the expression of these proteins while sustaining SPINK1 levels might have a clinical benefit in BRAF V600E‐positive colorectal adenocarcinoma." (PMID 29193645, 2018). "As PD98059, a MEK1 inhibitor, was not able to affect SPINK1 secretion or MEK and ERK phosphorylation, our data implicate MEK2 as a critical protein in the MAPK pathway in colorectal adenocarcinoma." (PMID 29193645, 2018).
cystic fibrosis (2 papers, 2017 to 2024). Autosomal recessive disorder caused by pathogenic variants in the CFTR gene (cystic fibrosis transmembrane conductance regulator), which encodes a chloride and bicarbonate channel expressed in epithelial cells, and follow the diagnosis criteria. "In particular, mutations that most commonly play a crucial role in the etiology of CP are associated with the PRSS1 (gene-encoding cationic trypsinogen), SPINK1 (Serine Protease Inhibitor Kazal type 1), CFTR (cystic fibrosis), CTRC, and CPA1 genes." (PMID 38978842, 2024). "A study by Schneider and colleagues found that coinheritance of cystic fibrosis causing CFTR variants with SPINK1 variants significantly increases the risk of idiopathic chronic pancreatitis, with 36% of the 53 patients with cystic fibrosis having a SPINK1 mutation." (PMID 29515728, 2017).
haemochromatosis (2 papers, 2013 to 2017). "We selected serine peptidase inhibitor, Kazal type 1 (SPINK1), a secretory trypsin inhibitor from the gene set over-expressed in haemochromatosis-related HCC and demonstrated its potential as a diagnostic marker in HCC." (PMID 23527199, 2013). "In our study, SPINK1-positive tumour cells were present in virtually every HCC case occurring in a background of haemochromatosis or ALD, it is in these cases where its use as a diagnostic marker would likely be most effective." (PMID 23527199, 2013).
liver cirrhosis (2 papers, 2017 to 2022). "Notably, through literature reviews, we found that CLDN10, CDKN3, CRHBP and NEK2 were reported to be associated with HCC, and SPINK1 was associated with liver cirrhosis." (PMID 28036264, 2017).
liver disease (2 papers, 2013). "This integrated analysis revealed SPINK1 as a potential diagnostic marker that was validated using a set of well-characterized samples from different liver diseases." (PMID 23527199, 2013). "To investigate the expression of SPINK1 in regenerative and dysplastic liver nodules further, we first looked at the SPINK1 mRNA expression level in 17 dysplastic nodules arising in HCV liver disease in the public microarray data." (PMID 23527199, 2013). "HCC arising in other background liver diseases still showed strong prevalence for SPINK1 (typically >75%), so its effective and reliable clinical use would require other indicative markers." (PMID 23527199, 2013). "We found significant fold changes for SPINK1, LEF1, TSPAN8, SPP1, OR2I1P and PTGFRN comparing HH-HCC with HH-liver disease and normal liver (p<0.05, one-way Anova)." (PMID 23527199, 2013). "SPINK1 mRNA expression was significantly higher in all HCC compared to the dysplastic nodules (p = 3.8×10−7) and there was a modest increase in SPINK1 comparing dysplastic nodules with background liver diseases (p = 0.04)." (PMID 23527199, 2013).
lung adenocarcinoma (2 papers, 2021 to 2023). A carcinoma that arises from the lung and is characterized by the presence of malignant glandular epithelial cells. "Patients with lung adenocarcinoma who had greater SPINK1 levels were linked to a less favorable overall survivals." (PMID 38093163, 2023). "Lung adenocarcinoma patients harboring higher SPINK1 levels were associated with unfavorable overall survival and progression-free survival." (PMID 33916984, 2021). "In lung adenocarcinoma, forced overexpression of SPINK1 increased PC9 and H1299 cell proliferation." (PMID 33916984, 2021). "SPINK1 was characterized as a prognostic marker for lung adenocarcinoma." (PMID 33916984, 2021).
ovarian clear cell cancer (2 papers, 2022). An invasive malignant neoplasm that arises from the ovary and is characterized by a predominance of clear and hobnail malignant epithelial cells. "Knockdown of SPINK1 suppressed the peritoneal metastasis of ovarian clear cell carcinoma in an animal experiment." (PMID 36053457, 2022). "Studies have shown that targeting the autocrine IL-6 (interleukin-6)-SPINK1 (serine peptidase inhibitor Kazal type) signal axis can inhibit the metastasis and spread of ovarian clear cell carcinoma, which provides a possibility while replicating the therapy." (PMID 35310909, 2022).
rectal cancer (2 papers, 2022 to 2025). A primary or metastatic malignant neoplasm that affects the rectum. "In rectal cancer, serine protease inhibitor Kazal type 1 (SPINK1) enhances the proliferation and migration of cancer cells by activating epidermal growth factor receptor-downstream ERK, p38, and JNK signaling pathways." (PMID 40421086, 2025). "The aim in this study was to demonstrate the clinicopathological role and progression of SPINK1 in rectal cancer (RC) patients undergoing concurrent chemoradiotherapy (CCRT)." (PMID 36053457, 2022).
Sepsis (2 papers, 2024 to 2025). Sepsis is defined as life-threatening organ dysfunction caused by a dysregulated host response to infection. "SPINK1 is among the most extensively studied members of the SPINK family, particularly in the contexts of sepsis and cancer." (PMID 40872585, 2025).
squamous cell carcinoma (2 papers, 2015 to 2023). A carcinoma arising from squamous epithelial cells. "This comparison showed an overlap of five genes (ETV4 (tumor non-malignant signature), STK32A, SPINK1, GOLT1A, KRT6A (adenocarcinomas—squamous cell carcinomas signature)) in the first case, and an overlap in one (KRT15) of the three most prominent genes in the second case." (PMID 36832225, 2023).
alcoholic pancreatitis (1 paper, 2017). Acute or chronic inflammation of the pancreas due to excessive alcohol drinking. "Most patients have heterozygous SPINK1 mutations leading to complex inheritance patterns, although SPINK1 variants have also been associated with autosomal recessive familiar pancreatitis, alcoholic pancreatitis and tropical pancreatitis." (PMID 29515728, 2017).
anemia (1 paper, 2021). A reduction in the number of red blood cells, the amount of hemoglobin, and/or the volume of packed red blood cells. "In this experimental setting, anemia treatment induced more expressions of SPINK1 mRNA and SPINK1 protein in tumor tissues according to the extent of tumor hypoxia, monitored as the CA9 mRNA levels (R2 = 0.6301 and R2 = 0.4449, respectively)." (PMID 34747365, 2021). "When blood flow to the xenografted tumors was decreased by ligaturing the tumor-bearing leg or by anemia treatment with PHZ injection, the expressions of SPINK1 mRNA and SPINK1 protein were significantly induced in our in vivo studies." (PMID 34747365, 2021). "However, it should be noted that there still remains a possibility that inflammatory stimulation, etc., caused by ligaturing or anemia treatment, but not hypoxic stimuli, might have induced the SPINK1 expression." (PMID 34747365, 2021). "Of note, when we applied the anemia model to nontumor-bearing mice, plasma SPINK1 levels were not increased at all, suggesting that circulating SPINK1 protein originated from the tumor xenografts, but not from other normal tissues." (PMID 34747365, 2021).
brain tumor (1 paper, 2022). "At the same time, the NALM-6 NOD/SCID model mice treated with SPINK1 showed obvious brain tumor cell infiltration, while most of the tumor cells of non-SPINK1 treated model mice were free of the pia mater." (PMID 35194087, 2022).
cholangiocarcinoma (1 paper, 2013). A carcinoma that arises from the intrahepatic biliary tree (intrahepatic cholangiocarcinoma) or from the junction, or adjacent to the junction, of the right and left hepatic ducts (hilar cholangiocarcinoma). "SPINK1 was not useful in distinguishing HPB cancer in this group, however, the cancers were predominantly pancreatic and cholangiocarcinoma and the control group predominantly gallstone disease." (PMID 23527199, 2013).
clear cell renal cell carcinoma (1 paper, 2021). "We intentionally used clear cell renal cell carcinoma tissues, approximately 95% of which harbor deficiency in functional VHL, to analyze whether SPINK1 expression depends on the VHL–HIF-1 axis in human cancers." (PMID 34747365, 2021).
cognitive decline (1 paper, 2025). "Specific expression of sPINK1 in mouse hippocampal neurons induced progressive pUb accumulation, accompanied by protein aggregation, proteostasis disruption, neuronal injury, neuroinflammation, and cognitive decline." (PMID 40742280, 2025).
cognitive deficits (1 paper, 2025). "Moreover, co-expression of Ub/S65A with sPINK1* ameliorated sPINK1*-induced cognitive deficits, suggesting a protective effect against pUb-caused impairments." (PMID 40742280, 2025).
colorectal tumor (1 paper, 2022). "Prior to explore the possible signaling pathway associated with SPINK1’s function, we evaluated the effects of SPINK1 on the growth of colorectal tumor HT29 cells." (PMID 37305325, 2022).
dysplastic (1 paper, 2013). "Secondly, we sought SPINK1 expression in additional macroregenerative nodules (MRN), low grade dysplastic nodules (LGN) and high grade dysplastic nodules (HGN) from 5 patients who had undergone liver transplantation, giving a total of 8 MRN, 7 LGN and 3 HGN." (PMID 23527199, 2013).
esophageal cancer (1 paper, 2021). A primary or metastatic malignant neoplasm involving the esophagus. "It has been reported in esophageal cancer that cells treated with a siRNA for SPINK1 were resistant to the antitumoral drug Cisplatin54." (PMID 33767253, 2021).
HMG-CoA lyase deficiency (1 paper, 2023). "The disease-specific treatment consisted of Leucine restricted diet in a patient (rWGS_19) with HMG-CoA lyase deficiency (MIM #246450) and pancrelipase in a homozygous proband and her heterozygous parents for a pathogenic SPINK1 variant (rWGS_21)." (PMID 36835410, 2023).
leukemia (1 paper, 2022). A malignant (clonal) hematologic disorder, involving hematopoietic stem cells and characterized by the presence of primitive or atypical myeloid or lymphoid cells in the bone marrow and the blood. "NALM-6 leukemia cells were then cultured with the endothelial monolayer to determine if their adhesive abilities were mediated by raised ICAM-1 and VCAM-1 expression in SPINK1-treated HUVECs." (PMID 35194087, 2022).
lymph node metastasis (1 paper, 2022). "Multivariable analyses revealed significantly prognostic candidates of OS were lymph node metastasis (p < 0.001), distant metastasis (p < 0.001), pathologic cancer stage (p = 0.003) and pre-CCRT SPINK1 (p = 0.003) in RC patients." (PMID 36053457, 2022).
malnutrition (1 paper, 2016). Inadequate nutrition resulting from poor diet, malabsorption, or abnormal nutrient distribution. "Genetic susceptibility due to genetic mutations particularly in SPINK1, CFTR, CTRC, and CLDN2/MORC4 genes is the most important factor and not malnutrition or dietary toxins for idiopathic CP suggesting the term ‘tropical pancreatitis’ is a misnomer." (PMID 29868209, 2016).
melanoma (1 paper, 2018). A malignant, usually aggressive tumor composed of atypical, neoplastic melanocytes. "Next, we analyzed the levels of secreted SPINK1 and its putative serine protease targets trypsin‐1 and trypsin‐2 in a panel of CRC and melanoma cell lines harboring either wild‐type or V600E BRAF." (PMID 29193645, 2018). "Notably, neither of the melanoma cell lines secreted SPINK1 or trypsins." (PMID 29193645, 2018).
metastatic cancer (1 paper, 2021). A carcinoma which has spread from the original site of growth to another anatomic site. "SPINK1 showed abundant expression in both primary and metastatic cancer cells but was significantly elevated in metastatic cancer cells." (PMID 34055623, 2021).
nonalcoholic steatohepatitis (1 paper, 2023). "Spink1 was also found to be upregulated in a nonalcoholic steatohepatitis (NASH)-HCC mouse model, suggesting that its upregulation is observed across different etiology-driven HCC." (PMID 38030644, 2023). "SPINK1 was also found elevated in nonalcoholic steatohepatitis (NASH)-related human HCC as compared to non-tumor counterparts." (PMID 38030644, 2023).
Obesity (1 paper, 2020). Accumulation of substantial excess body fat. "Obesity and inherited factors such as SPINK1 mutations have a proven association." (PMID 33403169, 2020).
oral squamous cell carcinoma (1 paper, 2025). "This study aimed to elucidate the functional role and molecular mechanisms of Serine Peptidase Inhibitor Kazal Type 1 (SPINK1) in oral squamous cell carcinoma (OSCC) through integrative analysis of single-cell RNA sequencing (scRNA-seq) data." (PMID 40904507, 2025). "Next, we will study the specific signaling pathways associated with SPINK1 and explore the potential molecular mechanisms by which SPINK1 affects the progression of oral squamous cell carcinoma." (PMID 40904507, 2025). "Thus, investigating SPINK1’s role and mechanisms in OSCC not only addresses critical gaps in understanding the pathogenesis of oral squamous cell carcinoma but also provides a theoretical foundation for developing novel therapeutic targets." (PMID 40904507, 2025).
papillary thyroid carcinomas (1 paper, 2014). "As far as the papillary thyroid carcinomas are concerned, FOS, FOSB and EGR1 genes were down-regulated, like CBX7, while SPP1, SPINK1 and STEAP1 were up-regulated." (PMID 24865347, 2014).
primary biliary cirrhosis (1 paper, 2013). "One case of primary biliary cirrhosis showed patchy periportal SPINK1 hepatocyte expression." (PMID 23527199, 2013).
serous ovarian adenocarcinoma (1 paper, 2015). "Among patients with high-grade serous ovarian cancers, similar survival was observed between groups with SPINK1-positive and SPINK1-negative tumors." (PMID 26437224, 2015).
thrombosis (1 paper, 2024). "Experts from France discovered that 19 of the 209 carriers of the SPINK1 mutation who had pancreatic symptoms also had thrombosis, suggesting that SPINK 1 may play a role in thrombosis." (PMID 39687810, 2024).
viral hepatitis (1 paper, 2013). An acute or chronic inflammation of the liver parenchyma caused by viruses. "Indeed, two previous reports have demonstrated that SPINK1 is expressed in HCC; a small study of twenty viral hepatitis-related HCC found that all were positive." (PMID 23527199, 2013).